PTH (parathyroid hormone)
Diseases named in the same sentence as PTH in open-access papers (continued):
Sharing a sentence is not in itself a finding about the gene and the disease.
primary hyperparathyroidism (continued). "Of those who obtained a PTH level, 50% had significantly elevated PTH levels consistent with the diagnosis of primary hyperparathyroidism." (PMID 36843806, 2023). "For sporadic primary hyperparathyroidism in which more than one gland is autonomously secreting excess PTH the term multiglandular parathyroid disease (MGPD) is recommended." (PMID 37806985, 2023). "In sporadic primary hyperparathyroidism, the correct preoperative diagnosis includes clinical evaluation, serum calcium, phosphorus and parathyroid hormone (PTH) dosage, ultrasound, and scintigraphic and radiological imaging." (PMID 37174047, 2023). "Primary hyperparathyroidism (PHPT) is a condition characterized by the overproduction of parathyroid hormone (PTH) from hyperfunctioning parathyroid glands." (PMID 37629746, 2023). "One of the most common endocrinological pathologies is primary hyperparathyroidism (PHPT), caused by excessive secretion of PTH from one or more parathyroid glands." (PMID 37568342, 2023). "Primary hyperparathyroidism (PHPT) is a disease characterized by the autonomous production of parathyroid hormone (PTH) by the parathyroid glands." (PMID 37959184, 2023). "In detail, surgically treated patients with sporadic primary hyperparathyroidism were divided into two groups, based on intraoperative parathyroid hormone (ioPTH) application." (PMID 37174047, 2023). "Our study included patients who were referred to the endocrinology clinic with a presumptive diagnosis of primary hyperparathyroidism, an isolated increased level of PTH, or reduced bone densitometry." (PMID 37065752, 2023). "The PTH gene over-expressed mice mimicking primary hyperparathyroidism showed adipose tissue browning leading to increased energy expenditure, reduced fat content, decreased body weight and muscle atrophy." (PMID 37484844, 2023). "Primary hyperparathyroidism (PHPT) is a disorder in which one or more parathyroid glands overproduce parathyroid hormone." (PMID 36843806, 2023). "Primary hyperparathyroidism (PHPT) is characterized by inappropriately increased secretion of parathyroid hormone (PTH) from the parathyroid glands." (PMID 36751183, 2023). "Io-PTH measurement's effectiveness in managing the parathyroid gland in the context of primary hyperparathyroidism, both adenoma and hyperplasia, have been reported." (PMID 37231458, 2023). "The concurrent measurement of the parathyroid hormone will help to distinguish between primary hyperparathyroidism and cancer." (PMID 37627135, 2023). "Of those who obtained a PTH level, 50% of them had significantly elevated PTH levels consistent with the diagnosis of primary hyperparathyroidism." (PMID 36843806, 2023). "Primary hyperparathyroidism, characterized by excessive parathyroid hormone (PTH) production, manifests symptoms resulting from the hormone’s effects on various body systems." (PMID 40729208, 2023). "Primary hyperparathyroidism (PHPT) is a common endocrinological pathology, caused by the overproduction of parathyroid hormone (PTH)." (PMID 37568342, 2023). "Primary hyperparathyroidism (PHPT) is a common endocrine disorder induced by the overproduction of parathyroid hormone (PTH)." (PMID 36960393, 2023). "Cinacalcet is a calcimimetic that decreases PTH, specifically demonstrated in a phase 3 study in patients with primary hyperparathyroidism, and increases phosphate reabsorption, which has demonstrated some benefits." (PMID 36511653, 2023). "A recent study of 1158 patients evaluated the success of limited exploration for primary hyperparathyroidism using ultrasound, sestamibi and intraoperative parathyroid hormone." (PMID 37806985, 2023). "BACKGROUND: Primary hyperparathyroidism (PHPT) is an endocrine disorder characterized by excessive secretion of parathyroid hormone (PTH) with upper-normal or elevated blood calcium levels due to primary thyroid gland pathology." (PMID 39069775, 2023).
primary hyperparathyroidism (continued). "The classic clinical vignette of primary hyperparathyroidism is well described as "bones, stones, abdominal moans, and psychiatric overtones" to reflect the effects of excess parathyroid hormone (PTH) and calcium." (PMID 37609099, 2023). "The initial diagnosis of patients with primary hyperparathyroidism (pHPT) typically starts with the identification of elevated serum calcium and parathyroid hormone (PTH) levels." (PMID 37627880, 2023). "Primary hyperparathyroidism (PHPT) is a common endocrine disorder that exorbitantly secretes parathyroid hormone (PTH) from the parathyroid glands." (PMID 35222284, 2022). "Primary hyperparathyroidism (pHPT), the condition in which the parathyroid glands produce more parathyroid hormone (PTH) than the body needs, is one of the most common endocrinopathies, and the only method that enables complete recovery is surgery." (PMID 36615844, 2022). "The primary hyperparathyroidism (PHPT) is characterized by the autonomous secretion of parathyroid hormone (PTH) by one or more parathyroid glands." (PMID 35647017, 2022). "Normocalcemic primary hyperparathyroidism (nPHPT) is one of newer presentation of primary hyperparathyroidism, in which PTH is elevated but serum calcium is normal." (PMID 36187131, 2022). "Primary hyperparathyroidism is related to autonomous overproduction of parathyroid hormone (PTH) by parathyroid glands." (PMID 36504377, 2022). "Primary hyperparathyroidism (PHPT) is a hypercalcemic disorder involving the over activity of parathyroid glands resulting in excess secretion of parathyroid hormone (PTH)." (PMID 36408083, 2022). "The aim of this study was to evaluate the relationship between parathyroid hormone and aldosterone in patients with primary hyperparathyroidism." (PMID 36389124, 2022). "Primary hyperparathyroidism (PHPT) results in an excess of PTH secretion, with a consequent increase in serum ionized calcium level." (PMID 35737325, 2022). "Primary hyperparathyroidism (PHPT) is the unregulated overproduction of parathyroid hormone (PTH), resulting in abnormal calcium homeostasis." (PMID 37435452, 2022). "Primary hyperparathyroidism (PHPT) is a condition that affects calcium metabolism due to parathyroid hormone (PTH) hypersecretion in one or more of the four parathyroid glands." (PMID 35419240, 2022). "Our results showed a strong positive correlation between PTH and renin concentration in patients with primary hyperparathyroidism." (PMID 36389124, 2022). "The purpose of the study was to assess the influence of parathyroid hormone on the circulating level of osteoprotegerin in patients with primary hyperparathyroidism by comparing it with healthy controls." (PMID 35950821, 2022). "Primary hyperparathyroidism (PHPT), caused by hypersecretion of parathyroid hormone (PTH) in one to four parathyroid glands, is a common endocrine disorder that is characterized by chronic elevation of serum concentrations of calcium." (PMID 35974370, 2022). "A total of 205 patients with primary hyperparathyroidism from a single adenoma were retrospectively evaluated and monitored with baseline PTH, PTH at 10 min and PTH at 20 min after adenoma excision." (PMID 35228624, 2022). "Primary hyperparathyroidism (PHPT) is a hypercalcemic disorder that occurs when one or more parathyroid glands produces excessive parathyroid hormone (PTH)." (PMID 36382757, 2022). "Primary hyperparathyroidism (PHPT) is a hypercalcemic disorder that occurs when one or more parathyroid glands produces excessive PTH." (PMID 36382757, 2022). "Normocalcemic primary hyperparathyroidism (NPHPT) is a disorder of the calcium metabolism characterized by elevated serum parathyroid hormone (PTH) levels with persistently normal serum calcium concentrations." (PMID 35437440, 2022). "The production of osteoprotegerin appears to be inhibited by parathyroid hormone in patients with primary hyperparathyroidism." (PMID 35950821, 2022).
primary hyperparathyroidism (continued). "Primary hyperparathyroidism in dogs is a possibly life-threatening condition, characterized by the excess of parathyroid hormone (PTH) secretion, which leads to an increase in serum ionized calcium level." (PMID 35737325, 2022). "The aim of the study was to examine the relationship between circulating serum levels of parathyroid hormone and aldosterone in patients with primary hyperparathyroidism." (PMID 36389124, 2022). "Firstly, the laboratory studies are performed to measure calcium, PTH, and phosphorus levels to confirm diagnosis of primary hyperparathyroidism." (PMID 36013465, 2022). "The proband (III.2) was diagnosed with primary hyperparathyroidism aged 26 years (peak corrected calcium 3.06mmol/L, normal range 2.5-2.55mmol/L; PTH 20pmol/L, normal range 1.5-6.9pmol/L)." (PMID 35323929, 2022). "Normocalcemic primary hyperparathyroidism (PHPT) is a newer phenotype of PHPT defined by elevated PTH concentrations in the setting of normal serum calcium levels." (PMID 36382756, 2022). "Primary hyperparathyroidism (PHPT) is an endocrine disorder characterized by excess secretion of parathyroid hormone (PTH), resulting from the hyperfunction of one or more of the parathyroid glands." (PMID 36382758, 2022). "Laboratory workup revealed normal thyroid function, nephrotic range proteinuria, elevated serum calcium level with an elevated parathyroid hormone level (PTH) consistent with primary hyperparathyroidism." (PMID 35440089, 2022). "When total calcium concentration is elevated, a second- or third-generation PTH assay should be used to measure PTH levels to confirm the diagnosis of primary hyperparathyroidism." (PMID 35261825, 2022). "Primary hyperparathyroidism (PHPT) is characterised by hyperfunctioning tissue in one or more of the parathyroid glands, causing an increase in parathyroid hormone (PTH)." (PMID 35196254, 2022). "Another experimental study using PTH gene over-expressed mice mimicking primary hyperparathyroidism showed similar characteristics of adipose tissue browning." (PMID 36176632, 2022). "The laboratory testing led to the detection of a very important level of parathormone PTH 1325.62 pg/ml (20 fold the normal level), confirming the diagnosis of primary hyperparathyroidism." (PMID 36578799, 2022). "Our study indicates that screening for normocalcemic primary hyperparathyroidism should be preferably done in autumn, as elevated PTH levels in spring are more likely to be related to 25OHD deficiency." (PMID 36187131, 2022). "On further evaluation, her PTHrP (Parathyroid Hormone Related Protein) was found to be normal and PTH (Parathyroid Hormone) came back elevated at 327 pg/ml (normal: 14 to 65 pg/mL), suggesting primary hyperparathyroidism." (PMID 34462682, 2021). "A diagnosis of primary hyperparathyroidism was made based on the elevated parathyroid hormone level and urinary calcium-to-creatinine clearance ratio." (PMID 33832152, 2021). "We have previously shown that ADGRG2 is enriched in parathyroid glands, is upregulated in parathyroid adenomas from patients with primary hyperparathyroidism, and its activation by P-15 elevates PTH secretion." (PMID 34234254, 2021). "Patients in cluster 1 had significantly higher serum total calcium, lower phosphate, and higher PTH levels than patients in cluster 2B, suggesting a condition of primary hyperparathyroidism due to inappropriate PTH release." (PMID 34977081, 2021). "Primary hyperparathyroidism (PHPT) describes an autonomous overproduction of parathyroid hormone (PTH) in one or more parathyroid glands." (PMID 33928428, 2021). "Patients with primary hyperparathyroidism have high concentrations of serum calcium or high concentrations of parathyroid hormone, or incorrect parathyroid hormone levels for serum calcium values." (PMID 33472651, 2021).
primary hyperparathyroidism (continued). "Primary hyperparathyroidism (PHPT) is an endocrine disorder of parathyroid glands characterized by excessive secretion of parathyroid hormone (PTH) with an upper normal or elevated blood calcium level." (PMID 34533017, 2021). "Primary hyperparathyroidism is hyperfunction of parathyroid glands characterized by overproduction of parathyroid hormone." (PMID 34829354, 2021). "Cluster 1 (n = 13) included patients with a primary hyperparathyroidism-like profile, suggesting a certain degree of autonomous PTH secretion from parathyroid glands." (PMID 34977081, 2021). "In a previous study of 845 patients with primary hyperparathyroidism, the main cause of operative failure of MIP using PTH monitoring was the surgeon’s inability to find the abnormal parathyroid gland." (PMID 33918800, 2021). "Further experiments in mice with primary hyperparathyroidism indicate that elevated PTH promotes browning of white adipose tissue, contributing to body weight loss." (PMID 34422722, 2021). "Primary hyperparathyroidism (PHPT) is a disorder of parathyroid hormone (PTH) hypersecretion by parathyroid gland(s) in patients with normal renal function, resulting in increased serum calcium concentration." (PMID 34456863, 2021). "Primary hyperparathyroidism (HPT), a disorder of mineral metabolism usually associated with abnormally elevated serum calcium, results from the uncontrolled release of PTH from one or several abnormal parathyroid glands." (PMID 33716975, 2021). "Primary hyperparathyroidism (PHPT) is an endocrine disorder resulting from excess secretion of parathyroid hormone (PTH), from one or more of the parathyroid glands." (PMID 33917470, 2021). "Subjects with primary hyperparathyroidism and thus elevated concentrations of PTH presented with higher MPV compared to age- and sex-matched healthy controls." (PMID 34222377, 2021). "Primary hyperparathyroidism (PHPT) is a disease of autonomous excessive secretion of parathyroid hormone (PTH) from pathologic parathyroid glands." (PMID 34722014, 2021). "Primary hyperparathyroidism (PHPT) results from an excess of parathyroid hormone (PTH) produced from an overactive parathyroid gland." (PMID 34020602, 2021). "Primary hyperparathyroidism (pHPT) is an endocrine disease related to excessive secretion of parathyroid hormone (PTH) from one or more hyperfunctioning parathyroid glands." (PMID 34943620, 2021). "Her laboratory tests showed high calcium (3.13 mmol/L) and very high parathyroid hormone (PTH 1036 pg/mL) but normal kidney function, suggesting primary hyperparathyroidism." (PMID 34450530, 2021). "Some evidence suggests that PTH has a role in this event since insulin resistance has been noted in patients with primary hyperparathyroidism." (PMID 32192220, 2020). "In this perspective, we provide a historical backdrop to this form of parathyroid disease and contend that this clinical presentation of excess parathyroid hormone, particularly in primary hyperparathyroidism, is still seen today." (PMID 32995697, 2020). "Primary hyperparathyroidism is a systemic endocrine disease that has significant effects on bone remodeling through the action of parathyroid hormone on the musculoskeletal system." (PMID 32148487, 2020). "Primary hyperparathyroidism (pHPT) is a common endocrine disorder due to excessive secretion of parathyroid hormone (PTH) from one or more hyperfunctioning parathyroid glands." (PMID 32604786, 2020). "A histomorphometric evaluation in primary hyperparathyroidism has depicted that PTH promotes periosteal resorption and intracortical porosity." (PMID 32192220, 2020). "In patients with primary hyperparathyroidism and in hypertensive patients, treatment with angiotensin-converting enzyme inhibitors decreased serum PTH levels." (PMID 32751307, 2020).
primary hyperparathyroidism (continued). "We report an observation of a primary hyperparathyroidism secondary to an ectopic secretion of intact parathyroid hormone in a 17-year-old girl with von Hippel-Lindau disease and bilateral pheochromocytoma." (PMID 32832168, 2020). "Higher whole PTH concentrations have also been described in humans with parathyroid carcinoma and primary hyperparathyroidism." (PMID 32582784, 2020). "Primary hyperparathyroidism (PHPT) is characterized by an autonomous dysregulated secretion of parathyroid hormone (PTH) from the parathyroid glands." (PMID 32953342, 2020). "Primary hyperparathyroidism (PHP) is the unregulated overproduction of parathyroid hormone (PTH) resulting in abnormal calcium homeostasis." (PMID 33348402, 2020). "Primary hyperparathyroidism (PHPT) is a result of the autonomous production of parathyroid hormone (PTH) from one or more abnormal parathyroid glands." (PMID 32555278, 2020). "Similar to other causes of primary hyperparathyroidism (PHPT), parathyroid cancer induces symptoms by an excessive, autonomous release of parathyroid hormone (PTH) into the bloodstream." (PMID 31661917, 2019). "In the presence of hypercalcemia, reduced PTH is expected and normal concentrations are sufficient for the diagnosis of primary hyperparathyroidism (PHPT)." (PMID 30916167, 2019). "Primary hyperparathyroidism is a relatively common endocrine disorder, which develops as a result of autonomous overproduction of parathyroid hormone (PTH) by parathyroid glands." (PMID 31367807, 2019). "Subsequently, there was a decreased phosphate (0.36 mmol/l [normal 0.81-1.62 mmol/l]) as well as 16-fold elevated serum level of parathyroid hormone (PTH, 1156 ng/l [normal 10-73 ng/l]), indicating a primary hyperparathyroidism." (PMID 31355036, 2019). "The goal of the present study was to determine the real incidence and characteristics of primary hyperparathyroidism with normal PTH and to evaluate if intraoperative PTH testing is useful in these patients." (PMID 31074404, 2019). "Primary hyperparathyroidism (PHPT) results from the inappropriate overproduction of parathyroid hormone from one or many parathyroid gland(s)." (PMID 31453033, 2019). "Primary hyperparathyroidism was suspected and confirmed by the elevated parathyroid hormone levels of 1453 pg/mL." (PMID 29936913, 2018). "In primary hyperparathyroidism (pHPT), quick intraoperative parathyroid hormone monitoring (IOPTH) is performed to predict complete excision of hyperfunctioning tissue and therefore cure." (PMID 30294345, 2018). "After parathyroidectomy, there was a complete biochemical remission of primary hyperparathyroidism in all patients with serum PTH, calcium, and PO4 reaching normal values within one to two months post-surgery." (PMID 30598042, 2018). "One patient showed elevated calcium and PTH levels and was consequently diagnosed with primary hyperparathyroidism and were treated surgically with parathyroidectomy after preoperative localization of parathyroid adenoma." (PMID 29439698, 2018). "All patients showed biochemical evidence of primary hyperparathyroidism with a mean serum calcium level of 2.78 ± 0.34 mmol/l and parathormone (PTH) level of 196.5 ± 236.4 pg/ml." (PMID 29516131, 2018). "Of these, one had primary hyperparathyroidism and the remaining 12 were diagnosed with secondary elevation of PTH levels." (PMID 30579337, 2018). "Distinguishing between primary hyperparathyroidism and malignancy is made readily by the concomitant measurement of parathyroid hormone which in primary hyperparathyroidism, again, will be markedly elevated." (PMID 28900835, 2017). "These include ectopic parathyroid hormone (PTH) production or primary hyperparathyroidism that coexists with malignancy." (PMID 29056680, 2017). "The levels of parathyroid hormone (PTH) should be undetectable or extremely low unless primary hyperparathyroidism is also present." (PMID 29348990, 2017).